FAM90A17 (family with sequence similarity 90 member A17)
Synonyms: FAM90A17P; FAM90A16P
Tractability: No criterion of Open Targets' tractability assessment is met for any kind of drug.
Gene: Protein-coding gene on chromosome 8 (7,746,034 to 7,749,044, forward strand). Ensembl gene ENSG00000285720.
Subcellular location (Human Protein Atlas): Nucleoplasm; Nucleoli
Homologues: Orthologues: mouse Fam90a1b (28% identical), mouse Fam90a1a (27% identical), rat Fam90a1l1 (26% identical). Paralogues in human: FAM90A16 (100% identical), FAM90A8 (99% identical), FAM90A9 (99% identical), FAM90A18 (99% identical), FAM90A19 (99% identical), FAM90A15 (98% identical), FAM90A13 (98% identical), FAM90A14 (98% identical), FAM90A23 (98% identical), FAM90A3 (98% identical), FAM90A5 (98% identical), FAM90A10 (98% identical), and 9 more.